LRP11 (LDL receptor related protein 11)
Synonyms: bA350J20.3; MANSC3
Tractability: Antibody: UniProt predicts a signal peptide or a membrane-spanning region; the Human Protein Atlas places it where antibodies can reach. PROTAC: ubiquitination databases record sites on it.
Gene: Protein-coding gene on chromosome 6 (149,818,757 to 149,864,424, reverse strand). Ensembl gene ENSG00000120256.
Subcellular location: Membrane
Subcellular location (Human Protein Atlas): Plasma membrane; Vesicles
Gene Ontology:
Molecular function: phosphoprotein binding
Biological process: multicellular organismal response to stress; response to cold; response to heat; response to immobilization stress; response to mechanical stimulus; response to starvation; response to water deprivation
Cellular component: plasma membrane; membrane
Genetic constraint (gnomAD): Loss-of-function variants: 20 observed, 27.43 expected, observed/expected ratio (o/e) 0.73, 90% interval 0.51 to 1.06. The synonymous counts are far from expectation, so gnomAD's model fits this gene poorly and the ratio says little. Missense variants: 560 observed, 478.39 expected, observed/expected ratio (o/e) 1.17, 90% interval 1.09 to 1.25. Synonymous variants: 291 observed, 211.8 expected, observed/expected ratio (o/e) 1.37, 90% interval 1.25 to 1.51.
Homologues: Orthologues: chimpanzee LRP11 (99% identical), macaque LRP11 (96% identical), pig LRP11 (86% identical), dog LRP11 (76% identical), rat Lrp11 (69% identical), mouse Lrp11 (69% identical), rabbit LRP11 (68% identical), zebrafish lrp11 (42% identical), guinea pig Lrp11 (37% identical), zebrafish spint1a (22% identical), zebrafish spint1b (21% identical), Drosophila melanogaster CG7565 (13% identical), and 6 more. Paralogues in human: SPINT1 (22% identical), KIAA0319L (15% identical), KIAA0319 (15% identical), WFIKKN1 (9% identical), WFIKKN2 (8% identical), AMBP (6% identical), TFPI (6% identical), SPINT2 (6% identical), WFDC8 (5% identical), TFPI2 (5% identical), EPPIN (3% identical), WFDC6 (3% identical), and 1 more.
Diseases named in the same sentence as LRP11 in open-access papers:
LRP11 is named in the same sentence as 34 diseases in open-access papers, as found by Europe PMC text mining. Sharing a sentence is not in itself a finding about the gene and the disease. The quoted sentences say what the papers report.
migraine (3 papers, 2023 to 2025). "These associations demonstrated that LRP11 was significantly associated with a decreased risk of any migraine (OR = 0.968, p = 1.27 × 10−6) and VD (OR = 0.958, p = 2.14 × 10−4)." (PMID 38898596, 2024). "Specifically, we found compelling evidence that LRP11 was associated with a decreased risk of both overall migraine and migraine with visual disturbances." (PMID 38898596, 2024). "LRP11 was significantly associated with the risk of any migraine (OR [odds ratio] = 0.968, 95% CI [confidence interval] = 0.955–0.981, p = 1.27 × 10−6) and significantly/suggestively associated with three migraine subtypes." (PMID 38898596, 2024). "Additionally, LRP11 showed suggestive associations with a decreased risk of two other migraine subtypes: migraine with aura and migraine with bad and recurrent headaches." (PMID 38898596, 2024). "We identified three tier 1 proteins (LRP11, ITIH1, and ADGRF5), whose genes have not been previously identified as causal genes for migraine in genetic studies." (PMID 38898596, 2024).
Alzheimer disease (2 papers, 2012 to 2022). A progressive, neurodegenerative disease characterized by loss of function and death of nerve cells in several areas of the brain leading to loss of cognitive function such as memory and language. "LRP11 is predicted to act in response to many biological processes linked to Alzheimer’s disease (AD)." (PMID 36613555, 2022).
cervical cancer (2 papers, 2024). A primary or metastatic malignant neoplasm involving the cervix. "Prior studies have indicated that LRP11 might be involved in cervical cancer and prostate cancer progression by increasing cell viability and accelerating the cell cycle." (PMID 38898596, 2024). "Although the prognostic value of LRP11 has been previously reported in prostate and cervical cancers, its role of LRP11 in LIHC remains unclear." (PMID 38425648, 2024). "However, our MR analysis did not found LRP11 was positively associated with cervical cancer or prostate cancer (p values <0.05)." (PMID 38898596, 2024).
hepatocellular carcinoma (2 papers, 2024 to 2025). A malignant tumor that arises from hepatocytes. "Meanwhile, related studies have shown that LRP11 is involved in the malignant progression of various tumors, but its role in hepatocellular carcinoma remains unclear." (PMID 39891099, 2025). "In addition, in vitro experiments verified the promoting effect of LRP11 on the migration, invasion, and colony formation capacity of hepatocellular carcinoma cells." (PMID 38425648, 2024).
prostate carcinoma (2 papers, 2024). A carcinoma that arises from epithelial cells of the prostate gland. "It has been reported that LRP11 activates β-catenin to induce PD-L1 expression in prostate cancer and that a high LRP11 level positively correlates with PD-L1 expression in cancer tissue." (PMID 38895099, 2024).
atherosclerosis (1 paper, 2021). A disease characterized by the build-up of fatty material and calcium deposition in the arterial wall resulting in partial or complete occlusion of the arterial lumen. "LRP11 has been implicated in the disruption of lipoprotein metabolism, and promotion of atherosclerosis." (PMID 33395447, 2021).
colon adenocarcinoma (1 paper, 2024). "Higher expression of LRP11 was observed in colon adenocarcinoma, lymphoid neoplasm diffuse large B cell lymphoma, liver hepatocellular carcinoma, pancreatic adenocarcinoma, prostate adenocarcinoma, rectum adenocarcinoma, stomach adenocarcinoma, and thyroid carcinoma." (PMID 38425648, 2024).
glioblastoma multiforme (1 paper, 2024). "In contrast, LRP11 expression decreases in glioblastoma multiforme and ovarian serous cystadenocarcinoma." (PMID 38425648, 2024).
lung carcinoma (1 paper, 2024). "On the contrary, we found suggestive evidence that LRP11 was negatively associated with lung cancer (OR = 0.970, p = 0.003)." (PMID 38898596, 2024).
retinal disease (1 paper, 2012). "Based on putative function and/or involvement in retinal disease, we selected 16 genes – Bach2, Cdr2, Dusp12, Esrrb, Gpsm2, Haus1, Kdm5b, Lman1, Lrp11, Lrrc2, Ncoa2, Plekha2, Ppargc1b, Trim36, Wisp1 and Zdhhc14." (PMID 22511886, 2012).
triple-negative breast carcinoma (1 paper, 2025). An invasive breast carcinoma which is negative for expression of estrogen receptor (ER), progesterone receptor (PR), and human epidermal growth factor receptor 2 (HER2). "LRP11 has been shown to drive tumor cell proliferation and metastasis in triple-negative breast cancer via the miR-149-3p/NRP2 axis, and its upregulation here correlates with the observed migratory phenotype." (PMID 40416783, 2025).
cancer (5 papers, 2014 to 2024). A tumor composed of atypical neoplastic, often pleomorphic cells that invade other tissues. "Because the expression of the LRP11 gene was upregulated in various cancers and was associated with the worst prognosis in LIHC, validation was performed on an additional six independent LIHC GEO databases." (PMID 38425648, 2024). "They showed that LRP11 expression may be regulated by epigenetic differences related to prognosis and is associated with cancer immunity." (PMID 38425648, 2024). "The present study aimed to explore the expression profile and prognostic value of LRP11 in liver hepatocellular carcinoma (LIHC) patients using various cancer databases and bioinformatic tools." (PMID 38425648, 2024). "Lrp1b has been mainly implicated in roles in the cell cycle, cellular growth regulation, and proliferation in the context of cancer, similarly to Lrp11, which has been related to oncogenesis and the stress response." (PMID 36648592, 2023). "Using the GEPIA2 database, mRNA expression of LRP11 was investigated in all cancers." (PMID 38425648, 2024). "Thus, LRP11 is deemed a major prognostic factor for LIHC in various human cancers, and further studies have focused on LIHC." (PMID 38425648, 2024). "Moreover, we observed that high LRP11 expression and high infiltration of immune cells, including macrophages, neutrophils, and MDSC, were associated with the worst patient prognosis, emphasizing the importance of LRP11 and its role in cancer-related immune processes." (PMID 38425648, 2024). "Thus, the functional analysis of LRP11 suggested that it may have a certain impact on tumor occurrence and prognosis and provide new insights into the recognition and challenges aimed at such signaling in cancer." (PMID 38425648, 2024). "In bioinformatics analysis, The Cancer Genome Atlas datasets showed increased LRP11 expression in tumor tissues compared to that in non-tumor tissues in various cancers." (PMID 38425648, 2024).
tumor (4 papers, 2024 to 2025). "LRP11 was mainly expressed in hepatocytes, T cells, and tumor-associated endothelial cells (TECs) in malignant cells." (PMID 38425648, 2024). "In this study, we found that higher LRP11 expression correlates with poorer clinical outcomes, indicating a potential tumor-promoting role for LRP11 in HCC." (PMID 39891099, 2025). "In vivo experiments further demonstrated that overexpression of RACK1 and USP5 alleviated the inhibitory effects of LRP11 knockdown on tumor proliferation, confirming their crucial role in mediating LRP11-driven HCC growth." (PMID 39891099, 2025). "RT-qPCR revealed significantly higher LRP11 mRNA levels in 60 HCC samples compared to paired non-tumor tissues." (PMID 39891099, 2025). "To further investigate key pathogenic factors in HCC, we analyzed the GSE14520 dataset and GEPIA database, LRP11 expression was found to be elevated in HCC tissues compared to non-tumor tissues." (PMID 39891099, 2025). "In the xenograft model, tumor size, weight, and proliferation rate were significantly reduced in the sh-LRP11 group compared to controls, while LRP11 overexpression had the opposite effect." (PMID 39891099, 2025). "Correlation between LRP11 expression level and gene markers of tumor infiltrating immune cells in TCGA-LIHC." (PMID 38425648, 2024). "The expression of LRP11 in tumors was significantly higher than that in non-tumor tissues and was considerably upregulated in the 52 LIHC-paired tumors." (PMID 38425648, 2024). "We also examined the effect of LRP11 expression on tumor microenvironment and epigenetic profiling and explored the role of LRP11 in gene networks and biological functions." (PMID 38425648, 2024). "Additionally, in both xenograft and lung metastasis models, LRP11 overexpression markedly enhanced tumor growth, invasion, and metastasis, providing additional support for its potential oncogenic role in HCC." (PMID 39891099, 2025). "Additionally, LRP11 expression was positively correlated with tumor size and stage." (PMID 39891099, 2025). "Therefore, the low expression of LRP11 in certain tumor tissues does not necessarily indicate a complete loss of its oncogenic function, but may reflect adaptive changes in tumor cells in response to the microenvironment or growth conditions." (PMID 39891099, 2025). "Analysis of LRP11 expression in HCC cells and tumor tissues revealed elevated levels compared to normal tissues." (PMID 39891099, 2025). "We then determined the relationship between LRP11 expression and clinicopathological features of LIHC, including sex, age, race, tumor stage, tumor grade, and histological subtype, using TCGA data from the UALCAN database." (PMID 38425648, 2024). "The elevated expression of LRP11 in fibroblast, endothelial, and malignant cells suggests a potential role in tumor development and progression, possibly through interactions with the ECM or influencing tumor cell migration and invasion." (PMID 40426943, 2025). "Although lower expression of LRP11 was observed in some HCC tissues, this may be influenced by factors such as tumor heterogeneity and changes in the tumor microenvironment." (PMID 39891099, 2025). "LRP11 shows a weak positive correlation with NK cells and negative correlations with both CD8+ T cells and Th17 cells, but its role in the tumor immune microenvironment (TME) of CRC appears to be more complex, potentially skewed toward immune suppression rather than activation." (PMID 40426943, 2025).
LRP11 also shares sentences with these, for which no sentence is quoted: allergic disease (1 paper); amyotrophic lateral sclerosis (1); binge eating disorder (1); breast carcinoma (1); diffuse large B-cell lymphoma (1); frontotemporal dementia (1); glaucoma (1); Headache (1); hereditary spastic paraplegia (1); lymphoid neoplasm (1); neurodegenerative disease (1); Optic neuropathy (1); ovarian serous cystadenocarcinoma (1); pancreatic adenocarcinoma (1); Parkinson disease (1); prostate adenocarcinoma (1); rectum adenocarcinoma (1); retinal ischemia (1); stomach adenocarcinoma (1); thyroid cancer (1); type 2 diabetes (1).